EGFR (epidermal growth factor receptor)
Diseases named in the same sentence as EGFR in open-access papers (continued):
Sharing a sentence is not in itself a finding about the gene and the disease.
cholangiocarcinoma (continued). "Amongst its mechanisms, genistein has shown a growth-inhibitory effect on human cholangiocarcinoma cells by reducing AKT and EGFR activation, as well as IL6 production, involving both oestrogen and oestrogen receptors, while also inhibiting inflammatory cell migration." (PMID 35884999, 2022). "As a key gene targeted AKT/EGFR signaling, ERRFI1 may be a binding target for some miRNAs and lncRNAs in various cancers, such as cholangiocarcinoma." (PMID 33789615, 2021). "In the current study, the inhibition of EGFR signaling by tyrosine kinase inhibitor is considered a potential therapeutic in cholangiocarcinoma; however, the results are not satisfactory." (PMID 32365487, 2020). "In contrast, the EGFR monoclonal antibody, cetuximab, had a modest therapeutic effect on the KRAS wild-type cholangiocarcinoma xenograft (TFK-1), but not the KRAS mutated xenograft (HuCCT1)." (PMID 29666220, 2018). "In cholangiocarcinoma cell types resembling RBE, up-regulation of EGFR Tyr1045 phosphorylation may be a potentially useful molecular alteration in EGFR-targeted therapy." (PMID 22591401, 2012). "Earlier, we have also reported that EGFR and VEGF overexpressions are frequent in cholangiocarcinoma (∼20 and 50%, respectively), that EGFR overexpression is an independent prognostic factor in IHCC, and that VEGF expression is associated with intrahepatic metastasis in IHCC." (PMID 19319137, 2009). "As VEGFR-2 was not expressed in any of cholangiocarcinoma cell lines, we assumed that the anti-proliferative effects of vandetanib observed in this in vitro study were mainly because of the inhibition of EGFR signalling." (PMID 19319137, 2009). "These in vitro results suggest that in cholangiocarcinoma cells, upregulation of the RAS/RAF/MAPK pathway by mutant KRAS might counteract the anti-growth effect of vandetanib by EGFR inhibition." (PMID 19319137, 2009). "In summary, we have shown that EGFR and VEGF expression is relatively common in cholangiocarcinoma." (PMID 18087285, 2008). "MUC1 interacts with EGFR and activates the EGFR/PI3K/Akt signaling pathway, thereby inducing the aggregation of Foxp3+Treg cells, enhancing the malignant phenotype of cholangiocarcinoma cells, and ultimately promoting the growth and metastasis of cholangiocarcinoma." (PMID 40070825, 2025). "However, growth factor signaling (EGFR, PDGFRβ) and downstream effectors (MAPK pathway) are more active in cholangiocarcinoma organoids and could provide potential druggable targets." (PMID 35764936, 2022). "Expression of EGFR or HER2 is known to be a prognostic factor in some cancers, but no previous study has clarified the influence of these molecules on prognosis in cholangiocarcinoma, probably because cholangiocarcinoma is a relatively rare cancer and collection of a large cohort is difficult." (PMID 18087285, 2008). "Epidermal growth factor receptor and VEGF mRNA were detected in all four cholangiocarcinoma cell lines, but VEGFR-2 mRNA was not expressed in any of them." (PMID 19319137, 2009).
neuroblastoma (115 papers, 2008 to 2025). Neuroblastoma (NB) is the most common solid, extracranial childhood tumor. "siRNA PLK1-LNPs achieved significant PLK1 gene silencing by more than 2-fold and improved cell targeting by 1.2 to over 4.5 times in EGFR+ high-risk neuroblastoma cells." (PMID 40880603, 2025). "A few neuroblastoma patients proved responsive to EGFR inhibitors such as Gefitinib, but only in association with other drugs." (PMID 30135355, 2018). "Whether cathepsin D plays an active role in EGFR-linked growth and progression of neuroblastoma remains to be elucidated." (PMID 35563171, 2022). "Increased EGFR expression also has been associated with the aggressive behavior of neuroblastomas." (PMID 35563171, 2022). "In particular, high expression of EGFR could be associated with RAS-MAPK pathway activation identified as a signaling pathway in relapsed neuroblastomas." (PMID 32948088, 2020). "The possible interaction between the lnc-LAMC2–1:1 rs2147578 polymorphism and the EGFR pathway may account for the increased risk of neuroblastoma of the G allele." (PMID 30285664, 2018). "Activation of EGFR, a paradigmatic receptor that is often associated with the mitogenic response in normal and cancer cells, is particularly critical for the execution of these biological events in neuroblastoma cells and in brain astrocytes." (PMID 22745828, 2012). "According to our analysis, five out of the six crizotinib-resistant mutants and all 11 neuroblastoma-associated ALK missense mutations lead to a residue that can be observed in related proteins at the same position (in marked difference to driver mutations in EGFR)." (PMID 24376513, 2013). "In an analysis of neuroblastoma tissue samples from 25 children, 81% of the tumours expressed EGFR, and it was shown to be localised both on the cell membrane and in the cytoplasm." (PMID 40426729, 2025). "Previous studies have demonstrated that EGFR inhibition serves as a promising therapeutic target in neuroblastoma." (PMID 40445424, 2025). "In neuroblastoma, the ErbB tyrosine kinases, such as EGFR and ERBB4, have been reported to promote cell growth and prevent apoptosis in preclinical models via the MAPK–ERK and PI3K–AKT49–51 pathways." (PMID 40229600, 2025). "A recently published study analysed EGFR in the context of alpha-synuclein aggregation in human neuroblastoma cells (SH-SY5Y)." (PMID 40940805, 2025). "EGFR is widely expressed in neuroblastoma cells and primary tumors, where it promotes cell proliferation." (PMID 40445424, 2025). "Supporting evidence from the literature further affirms these observations: K. africana fruit extract induced cell death and inhibited proliferation in neuroblastoma cells in a dose- and time-dependent manner, modulating NF-κB and EGFR signaling pathways." (PMID 41515404, 2025). "Taken together, our data indicate that silencing of PHLDA1 sensitizes IMR-32 neuroblastoma cells to EGFR inhibitors treatment." (PMID 38495105, 2024). "We demonstrated that cathepsin D (CD) counteracts EGF-induced neuroblastoma cell growth in 2D by downregulating EGFR/MAPK signaling." (PMID 38611021, 2024). "Since the high expression of EGFR has been associated with enhanced tumor growth and chemoresistance in neuroblastomas, the pharmacological inhibition of EGFR is a clinical approach widely used for cancer treatment." (PMID 38611021, 2024). "Recruitment of UBE4B to endosomal membranes is dependent on binding with Hrs, and we demonstrated that UBE4B ubiquitin ligase activity is required for appropriate EGFR trafficking and lysosomal degradation in neuroblastoma cells." (PMID 37957138, 2023). "UBE4B gene expression is strongly associated with neuroblastoma patient outcomes, and UBE4B ubiquitin ligase activity on the endosomal membrane surface is required for appropriate EGFR trafficking and lysosomal degradation in neuroblastoma cells." (PMID 37957138, 2023).
neuroblastoma (continued). "This work aimed to understand the mechanisms linking EGFR stimulation and cathepsin D expression with neuroblastoma progression and prognosis." (PMID 35563171, 2022). "Serum withdrawal triggers EGFR-dependent activation of the PI3K/Akt pathway in neuroblastoma cells, inducing the upregulation of P2rx7 gene expression, which in turn promotes the survival/proliferation of cancer cells in the absence of trophic support." (PMID 36589747, 2022). "We investigated the biochemical pathways downstream to EGFR stimulation in human SH-SY5Y neuroblastoma cells engineered for overexpressing or silencing of CD expression." (PMID 35563171, 2022). "In the present study, we interrogated datasets from the TCGA database to determine the clinical relevance of CTSD status in pediatric neuroblastoma patients highly expressing EGFR." (PMID 35563171, 2022). "In this context, it is of relevance that ERK 1/2 activation by EGFR was reduced in the neuroblastoma cells overexpressing CD." (PMID 35563171, 2022). "We previously reported that serum deprivation triggers EGFR-dependent activation of the PI3K/Akt pathway in neuroblastoma N2a cells, which is crucial for the Sp1-dependent transcription of P2rx7 gene." (PMID 36589747, 2022). "Gene correlation analysis in pediatric neuroblastoma patients revealed that individuals bearing a high EGFR transcript level have a good prognosis only when CTSD (the gene coding for the lysosomal protease Cathepsin D, CD) is highly expressed." (PMID 35563171, 2022). "EGFR, a receptor protein involved in cell proliferation and invasiveness, is known to be overexpressed in human neuroblastoma cells." (PMID 34748597, 2021). "DpC succeeded in downregulating the levels of EGFR in all four studied neuroblastoma cell lines; thus we identified another shared effect of thiosemicarbazone treatment in this type of cancer." (PMID 35008802, 2021). "We previously reported on the PDGFRB-induced transactivation of EGFR in medulloblastoma and neuroblastoma cells that was effectively abrogated with imatinib and sunitinib." (PMID 34422720, 2021). "Others have also reported that high-risk neuroblastoma associated with MYCN amplification cooperates with Gab2, a scaffold protein that amplifies EGFR signaling." (PMID 32260356, 2020). "Although IIF induced a significant increase in mRNA NDRG1 expression and EGFR (mRNA, total protein, and p1068EGFR) decreased, the real meaning and role of EGFR activity in neuroblastoma require further investigation." (PMID 30135355, 2018). "Previous studies revealed that the EGF receptor is overexpressed in neuroblastoma tissues and cells, and anti-EGFR agents are potential targeted therapies for neuroblastoma." (PMID 30285664, 2018). "Taken together, these results show that afatinib inhibits neuroblastoma growth both in vitro and in vivo by suppressing EGFR-mediated PI3K/AKT/mTOR signaling." (PMID 27902463, 2017). "Performing a factorial matrix-design combinatorial drug screen on the SH-SY5Y neuroblastoma cells line we found that the FDA approved EGFR/HER2 tyrosine kinase inhibitor lapatinib strongly synergized with YM155." (PMID 28596528, 2017). "The data also suggest that there are different routes to cell proliferation in neuroblastoma, such as the distinct mechanisms activated by the EGFR group, or KIT." (PMID 25884760, 2015). "Another study demonstrated that treatment of chemosensitive neuroblastoma cells with cisplatin reversibly increased EGFR expression and that cisplatin-resistant cells exhibited enhanced EGFR expression dependent of the presence of cisplatin." (PMID 25216514, 2014). "Cisplatin-resistant neuroblastoma cells express enhanced levels of epidermal growth factor receptor (EGFR) and are sensitive to treatment with EGFR-specific inhibitors." (PMID 24758355, 2014).
neuroblastoma (continued). "Several recent studies have identified functions of Toca-1 in regulating filopodia formation and vesicular trafficking in neuroblastoma cells, EGFR trafficking to lysosomes, and EGFR-driven cell motility and invasion." (PMID 25547174, 2014). "EGFR trafficking has been demonstrated to be regulated by PKA activity, and inhibition of PKA activity results in internalization of the EGFR in neuroblastoma N2a cells." (PMID 18380891, 2008). "Additionally, EGFR signaling reportedly regulated Mcl-1 survival action in neuroblastoma by disrupting Bim to Mcl-1." (PMID 38888847, 2025). "Two studies have investigated the expression of EGFR in neuroblastoma." (PMID 40426729, 2025). "The activation of EGFR is linked to the proliferation, migration, and invasion of neoplastic cells, and it is found to be overexpressed in several cancer types, including SH-SY5Y neuroblastoma cells." (PMID 40445424, 2025). "The attached BsAbs had dual recognition of methoxy PEG of nanocarriers and neuroblastoma EGFR." (PMID 40880603, 2025). "Serum withdrawal triggers EGFR-dependent activation of the PI3-kinase/Akt pathway in neuroblastoma cells, resulting in the phosphorylation of the Sp1 transcription factor and the induction of P2X7R expression, which promotes cell proliferation in the absence of trophic support." (PMID 37776398, 2024). "CD3/EGFR BiTEs alongside an anti-EGFRVIII CAR-T cell was another example designed for neuroblastoma, which could successfully target the tumor cells expressing EGFR." (PMID 36419058, 2022). "These preliminary data provided the rationale to speculate that cathepsin D could be involved in EGFR regulation of neuroblastoma growth." (PMID 35563171, 2022). "Our data suggest that chemotherapeutics that inhibit the EGFR pathway, along with stimulators of cathepsin D synthesis and activity, could benefit neuroblastoma prognosis." (PMID 35563171, 2022). "EGFR/HER1, a receptor protein involved in cellular growth and invasiveness, is found frequently overexpressed or aberrantly activated in human neuroblastoma cells, and its inhibition or decreased phosphorylation causes tumor growth suppression and apoptosis in neuroblastomas." (PMID 35563171, 2022). "Other rat sarcoma (RAS) mutations (specifically KRAS exon 3 and 4, and neuroblastoma (N]RAS) and v-raf murine sarcoma viral oncogene homolog B1 (BRAF) mutations may similarly reduce the benefit of anti-EGFR therapies." (PMID 34298750, 2021). "In addition, fusing anti-EGFR nanobodies to the GPI anchor of neuroblastoma EVs resulted in a significantly increased capacity of these EVs to bind tumor cells that overexpress the EGFR." (PMID 33430152, 2021). "uPAR plays an important role in the survival of a neuroblastoma cell line through a mechanism probably involving the EGFR and its downstream effectors, since uPAR blocking results in the impairment of EGFR to activate signals for survival of mouse neuroblastoma cells." (PMID 33923400, 2021). "Indeed, DpC succeeded in moderately decreasing the levels of total EGFR over the course of 2 days in all tested neuroblastoma cell lines." (PMID 35008802, 2021). "Moreover, in neuroblastoma, expression of EGF and EGFR has been associated with aggressive behavior both in vitro and in vivo." (PMID 31293052, 2019). "Moreover, the identification of EGFR as a transcriptional regulator of PTHLH in neuroblastoma provides a novel therapeutic opportunity to promote a less aggressive tumor phenotype through irreversible inhibition of EGFR tyrosine kinase activity." (PMID 31293052, 2019). "Conversely, we here show that PTHLH is controlled by EGFR in neuroblastoma." (PMID 31293052, 2019). "Moreover, neuroblastoma cells were exposed to the EGFR irreversible inhibitor canertinib (CI‐1033) after analyzing IC50 concentrations and cell viability was inhibited at low micromolar concentrations." (PMID 31293052, 2019).
neuroblastoma (continued). "Additionally, neuroblastoma cells can acquire resistance to the BCL-2 inhibitor ABT-737 by upregulating EGFR and develop a dependence on MCL-1, which can be effectively countered by combining erlotinib with a BCL-2 inhibitor." (PMID 31150457, 2019). "Our study supports the idea that EGFR is a potential therapeutic target in neuroblastoma." (PMID 27902463, 2017). "However, the inhibitory effects of Vandetanib on VEGFR2 and EGFR signaling cannot be distinguished with respect to neuroblastoma cell survival." (PMID 24349301, 2013). "Therefore human LA-N-5 neuroblastoma cells grown in serum-free media exhibited γ-secretase and EGFR-dependent clonal growth as tumorspheres and were enriched via serial passage." (PMID 19156211, 2009). "Similarly, we also showed that the NSCLC model acquired hyperactivation of EGFR after exposure to lorlatinib (i.e., H3122-LR100 cell line), whereas the lorlatinib-resistant neuroblastoma cell line GLB-Ga-LR1000 was associated with the hyperactivation of EGFR and ErbB4." (PMID 39767726, 2024). "Further, in silico transcriptome analysis revealed that neuroblastoma patients with high EGFR and high CTSD levels had a better prognosis compared to patients bearing high EGFR and low CTSD." (PMID 35563171, 2022). "There are no studies that have focused on this type of activity of GEF or LAP; however, the multikinase inhibitor SUN has been previously shown to target a number of unconventional RTKs, including EGFR, FGFR, TrkA, and TrkB, in neuroblastoma cells." (PMID 36160437, 2022). "Our previously obtained results demonstrate that uPAR knockout inhibits EGFR/ERK signaling axis and Akt activation and leads to attenuated cell proliferation in neuroblastoma." (PMID 35205745, 2022). "Here, we therefore aimed to investigate the molecular effects of DpC on a panel of neuroblastoma cell lines to evaluate its impact on some of the most prominent molecules (MYC oncoproteins, NDRG1, and EGFR) in neuroblastoma." (PMID 35008802, 2021). "Specifically, treatment with DpC proved to target some of the major molecular targets in neuroblastoma, namely the MYC proteins and both total and phosphorylated levels of EGFR." (PMID 35008802, 2021). "Neuroblastomas widely express EGFR, and we used the same EGF-mimicking peptide to target nanoconstructs into nuclei of neuroblastoma cells as well." (PMID 34777621, 2021). "Prior studies have shown that treatment of neuroblastoma tumors with vandetanib, a RET, VEGFR, and EGFR inhibitor, resulted in a significant decrease in tumor angiogenesis in vivo." (PMID 31695841, 2019). "EGFR is a gene that is directly downregulated by N-MYC, which is often overexpressed in neuroblastoma, and previously demonstrated to be a molecular target of both EGCG and IIF." (PMID 30135355, 2018). "ML141 was recently used as a potent Cdc42 inhibitor in cancer stem cells to downregulate epidermal growth factor receptor (EGFR) and redox/Fyn/c-Cbl signaling pathways, and to regulate apoptosis in neuroblastoma cells." (PMID 29921325, 2018). "ALK, FGFR1, RET, PDGFRA, DDR2, EGFR, and IGF1R were enriched in endosomes from two or more neuroblastoma cell lines, but there were profound differences among cell lines." (PMID 25884760, 2015). "Thus, we extended the research to further investigate the role of EGFR and its connotation with PHLDA1 in human neuroblastoma." (PMID 38495105, 2024). "Additionally, the heatmap depicting the mRNA expression (bottom part) indicates that most neuroblastoma patients display high levels of MYCN, while the mRNA levels of EGFR, EGF, MAPK1 and CTSD are low or very low." (PMID 38611021, 2024). "In our previous work, we found that prognosis was improved in patients bearing a neuroblastoma with high expression of CTSD regardless of the expression of EGFR." (PMID 38611021, 2024).